HDAC3 (histone deacetylase 3)
Diseases named in the same sentence as HDAC3 in open-access papers (continued):
Sharing a sentence is not in itself a finding about the gene and the disease.
cancer (continued). "It is in line with the result recently described for the lncRNA-LET, a lncRNA generally downregulated in carcinomas, that was shown to be repressed by histone deacetylase 3 under hypoxic conditions." (PMID 24238219, 2013). "Previous studies suggest that the class I HDAC3 plays an important role in regulating DNA damage response and is a theoretical target for therapy in cancer cells." (PMID 22531354, 2012). "Results from cancer cell lines reveal that sodium butyrate inhibits Myc expression and implicate HDAC3 in this process." (PMID 22582024, 2011). "For example, HDAC2 and HDAC3 are over-expressed in multiple forms of cancer, and contribute as well to neurodegeneration." (PMID 22582024, 2011). "In the present paper, we have demonstrated that HDAC3 and HDAC7 are involved in the endogenous ATX expression regulation, which is supported by the loss- and gain-of-function studies in multiple cancer cell lines." (PMID 21314984, 2011). "The use of HDAC3 inhibitors may help mitigate excessive STING pathway activation as a potential preventive strategy against cancer development." (PMID 40006729, 2025). "Recognizing the potential for higher therapeutic efficacy by targeting both cancer cells and the bone marrow niche, we examined whether targeting HDAC3 in BMSCs could enhance the anti-AML effects of venetoclax." (PMID 40623992, 2025). "Additionally, studies have shown that high HDAC3 expression correlates with resistance to certain therapies, making it a potential target for cancer treatment." (PMID 40006729, 2025). "While all four classes of HDACs have been implicated in various cancers, Class I HDACs (HDAC1, HDAC2, HDAC3, and HDAC8) are generally considered the most directly and frequently associated with tumorigenesis and are often the primary targets in initial cancer therapeutic strategies." (PMID 41440016, 2025). "HDAC3 has been increasingly recognized for its role in cancer development and progression." (PMID 40006729, 2025). "Combining HDAC3 inhibitors with ferroptosis inducers such as RSL3 or Erastin could represent a promising therapeutic strategy to eliminate treatment-refractory cancer cells." (PMID 40947430, 2025). "HDAC3 inhibitors are being explored in clinical trials to disrupt its activity, aiming to slow tumor growth and improve patient outcomes, either alone or in combination with other cancer treatments." (PMID 40006729, 2025). "HDAC3 inhibitors, when combined with DNA-damaging agents or immune checkpoint inhibitors, can sensitize tumor cells to these treatments, leading to more effective cancer cell eradication." (PMID 40006729, 2025). "Targeting HDAC3 could therefore represent a promising strategy to enhance anti-cancer immunity by reprogramming the TIME and overcoming immune evasion mechanisms employed by tumors." (PMID 40006729, 2025). "To date, reviews have been published devoted to either monotherapy of cancer, lung diseases (HDAC3), using HDAC inhibitors and the effect of HDAC inhibitors on the immune system, or the antitumor activity of commercial chemotherapy drugs, for example, cisplatin and other platinum-based drugs." (PMID 40943548, 2025). "Overall, chidamide’s ability to inhibit HDAC3 and subsequently suppress NF-κB signaling and inflammatory gene expression highlights its potential as a therapeutic agent for inflammatory diseases and cancers." (PMID 39040100, 2024). "HDAC3 influences cell differentiation, apoptosis, cancer progression, and the cell cycle." (PMID 38805168, 2024). "We examined the expression pattern of HDAC3 in various cancers using publicly available datasets." (PMID 38805168, 2024). "Thus, HDAC3 seems to promote FP-RMS radioresistance partly by preserving the cancer cells population from IR-induced apoptosis by promoting cancer stemness." (PMID 39107280, 2024).
cancer (continued). "Overall, this study embarks on a journey to explore the potential of repositioning FDA-approved drugs as HDAC3 inhibitors, addressing the pressing need for novel therapeutic strategies in the battle against complex diseases, with a particular emphasis on cancer." (PMID 39005934, 2024). "For patient su008, entinostat, a benzamide histone deacetylase inhibitor targeting HDAC1 and HDAC3 treated as monotherapy or combinatorial drug together with immunotherapy to various cancers, was ranked 4th in comboSC prediction results as a drug that can be paired with immunotherapy." (PMID 38041202, 2023). "In addition, as a novel non-invasive biomarker, extracellular vesicle expression of miR-193b-3p is upregulated in HeLa cancer cells and directly targets HDAC3; it also attenuates neuroinflammation in early brain injury after aSAH in mice." (PMID 36860299, 2023). "HDAC3 was highly expressed in multiple cancer types, including LUAD." (PMID 37553641, 2023). "Moreover, RT-qPCR analysis revealed that SIRT5 and HDAC3 expression levels in cancer tissues were significantly higher than in normal tissues (p < 0.05)." (PMID 37705968, 2023). "Based on a study with human maxillary carcinoma cells under acidic conditions, HDAC3 inhibition combined with hyperthermia may provide an efficient therapeutic approach for cancer." (PMID 34973135, 2023). "Previous studies have shown a contributing role of HDAC3 in the compendium of clinical cancers." (PMID 34973135, 2023). "Because HDAC3 has been reported to regulate the phosphorylation of STAT3 Y705 in other cancer types, we speculated that HDAC3 might influence the phosphorylation of STAT3 Y705 via activation of CDK1." (PMID 37743465, 2023). "Because glutamine starvation prevents GS degradation through enhancing HDAC3‐GS interaction, ways to weaken HDAC3‐GS interaction could be a direction to develop cancer inhibiting strategies." (PMID 35187863, 2022). "The screened hit compounds may act as selective inhibitors of HDAC3 and may be used for the treatment of cancer subtypes." (PMID 35110603, 2022). "Interestingly, in addition to SKI, many other putative HDAC3 deacetylation substrates have cancer related functions." (PMID 35994477, 2022). "Moreover, HDAC3 inhibitors were effectively tested on various cancer subtypes, neurodegenerative disorders, cardiac diseases, atherosclerosis, human immunodeficiency virus, and inflammatory diseases." (PMID 35110603, 2022). "Interestingly, these proteins, in addition to other identified HDAC3 targets including MB21D2 and the melanoma-associated antigen MAGED1, also have cancer-associated functions." (PMID 35994477, 2022). "In addition, it has been reported that suppression of HDAC3 sensitized cancer cells that had developed resistance to chemotherapies." (PMID 35646715, 2022). "Selective inhibition of HDAC3 has shown a vast prospect in the treatment of cancer." (PMID 35910736, 2022). "Nevertheless, investigations into the suggested targets, EphB2 and HDAC3, using selective inhibitors might prove fruitful given their implications in other cancers." (PMID 35666359, 2022). "Furthermore, TH34, an HDAC6/8/10 inhibitor, and droxinostat, an HDAC3/6/8 inhibitor, have demonstrated anti-cancer effects in several cancer types." (PMID 35955780, 2022). "Overexpression of HDAC3 is observed in many types of cancers, particularly leukemia and lymphoma." (PMID 34502048, 2021). "HDAC3 is a member of HDACs, and plays critical roles in cancer progression." (PMID 34335948, 2021). "Furthermore, aberrant HDAC3 expression reversed the increased histone H3 acetylation of the PD-L1 promoter and decreased PD-L1 expression in drug-resistant cancer cells." (PMID 32024543, 2020). "HDAC3 regulates the acetylation and transcription of c-Jun in cancer cells." (PMID 32024543, 2020). "In this study, HDAC3 expression was markedly decreased in drug-resistant cancer cells." (PMID 32024543, 2020).
cancer (continued). "The drug-resistant cancer cells expressed lower HDAC3 levels than their parental counterparts." (PMID 32024543, 2020). "Collectively, a potent HDAC3 inhibitor was discovered, which could be utilized as a lead compound in the development of new drugs for cancer treatments." (PMID 33178617, 2020). "Furthermore, HDAC3 overexpression significantly decreased histone H3 acetylation of the PD-L1 promoter region and PD-L1 expression in the drug-resistant cancer cells." (PMID 32024543, 2020). "Next, HDAC3 expression was compared in the drug-resistant cancer cells and parental cells." (PMID 32024543, 2020). "We then investigated whether the activity of HDAC3 could affect cMYC, since intracellular cMYC showed instability and is regulated by acetylation-related degradation at the K323 site in cancer cells." (PMID 30866966, 2019). "The purpose of our study was to explore the role of cMyc in regulating pyruvate metabolism, as well as to investigate whether the inhibitory effect of pyruvate on HDAC3 could hold promise in the treatment of cancer cells." (PMID 30866966, 2019). "In another report, lncRNA-LET (low expression in tumor) is regulated by histone deacetylase 3 (HDAC3), which may be involved in hypoxia-induced cancer metastasis." (PMID 31906046, 2019). "Overexpression of HDAC3 is correlated with poor prognosis in various cancers." (PMID 30583572, 2018). "It has been reported that histone deacetylase 3 (HDAC3) regulates responses to anti-cancer drugs, angiogenic potential, and tumorigenic potential of cancer cells in association with cancer-associated genes (CAGE), and in particular, a cancer/testis antigen gene." (PMID 30583572, 2018). "The role of HDAC3 in cancer development is known to be tissue-specific." (PMID 30583572, 2018). "Overexpression of HDAC3 overcomes resistance of Malme3MR cells to anti-cancer drugs." (PMID 30583572, 2018). "MiR-326 directly regulated by HDAC3 can regulate responses to anti-cancer drugs." (PMID 30583572, 2018). "inhibited HDAC3 to decrease the level of IL-6 produced by the cancer cells." (PMID 29254283, 2017). "Increased HDAC3 expression might therefore be an important mechanism for facilitating cancer cell proliferation in CCA." (PMID 29245911, 2017). "It has previously been shown that HDAC1, HDAC3, and HDAC4 might be associated with resistance to chemotherapy and poor prognosis in cancer patients." (PMID 26683361, 2016). "miR-326 forms a feedback loop with HDAC3 and regulate the response to anti-cancer drugs." (PMID 26863629, 2016). "Expression of Class I HDAC enzymes (including HDAC3) is increased in cancers." (PMID 27874833, 2016). "A detailed study of the functionality of such an association may help us to understand the mitotic process and provide new targets, such as HDAC3, H1.3, and other complex components, for cancer therapy." (PMID 26663086, 2016). "Pharmacological and molecular inhibitions of HDAC3 decreased IL-6 levels in cancer cells." (PMID 26745602, 2016). "Our study suggests that HDAC3-specific inhibitors may be particularly adept at leveraging this aspect of anti-cancer activity." (PMID 27874833, 2016). "Consistent with this hypothesis, a meta-analysis of human solid tumours showed that HDAC3 was one of the most frequently upregulated genes in cancer cells." (PMID 26077467, 2015). "This suggests that cancer cells may resist apoptotic cell death, at least in part, through HDAC3-mediated mechanisms." (PMID 26077467, 2015). "The novel pathway identified may help generate new anti-cancer strategy by targeting HDAC3 and its related molecules." (PMID 25623232, 2015).
cancer (continued). "Therefore, we set out to determine the effects of selective HDAC3 inhibition using RGFP966 on cancer cell growth." (PMID 23894374, 2013). "In addition, these HDAC3-selective inhibitors induced growth inhibition of cancer cells, and activated HIV gene expression in latent HIV-infected cells." (PMID 23874714, 2013). "Ac-histone 4 protein levels markedly increased suggesting that NBM-HD-1 might affect HDAC-3 and increase Ac-histone 4 expressions in nuclei of cancer cells." (PMID 22046195, 2012). "Additionally, compound 8a profiled promising PK properties, and in in vivo assays, it exhibited promising antitumor activity in the 4T1-Lucxenograft model, which is strongly related to HDAC3 impairment, thusconfirming compound 8a as a promising candidate to beevaluated in such cancer types." (PMID 40637413, 2025). "The precise molecular mechanisms underlying HDAC4's role in cancer remain incompletely understood, but it may involve interactions with the corepressor complex NCOR1/NCOR2/HDAC3 and influence the transcription landscape of cancer cells through epigenomic reprogramming." (PMID 38911380, 2024). "It is tempting to speculate that an accumulation of NOXA due to an inhibition of HDAC2 and a disruption of the SIN3 complex combined with compromised genomic integrity due to an inhibition of HDAC3 are molecular mechanisms through which KH16 kills cancer cells." (PMID 37509312, 2023). "In addition, treating Huh7 cells (a hepatocyte-derived carcinoma cell line) with the HDAC3 inhibitor RGFP966 increased YAP immunofluorescence in the nucleus, and Western blot analysis confirmed that RGFP966 decreased YAP in the cytoplasm and increased YAP in the nucleus." (PMID 38034086, 2023). "Moreover, HDAC3 inhibitor has been found to hold strong proapoptosis ability and might suppress cancer stemness." (PMID 36175803, 2022). "Therefore, the screened hit compounds may act as a potent and selective inhibitor of HDAC3 and may find applications for the treatment of various cancer subtypes and other human disorders regulated by HDAC3." (PMID 35110603, 2022). "We conclude that the screened hit compounds may act as potent inhibitors of HDAC3 and further preclinical and clinical studies may pave the way for developing them as effective therapeutic agents for the treatment of different cancers and neurodegenerative disorders." (PMID 35110603, 2022). "Therefore, the screened hits may act as potent and selective inhibitors against HDAC3 and may be used for the treatment of different types of cancers." (PMID 35110603, 2022). "Therefore, these hit compounds may act as potent and selective inhibitors of HDAC3 and may be used for the treatment of cancer subtypes." (PMID 35110603, 2022). "Moreover, HDAC3 enhances aerobic glycolysis in cancer cells." (PMID 35896951, 2022). "In addition, it is suggested that HDAC3 is involved in cancer progression." (PMID 34502048, 2021). "Moreover, HDAC3 downregulates the invasion, tumorigenic and angiogenic response of cancer cells." (PMID 33973278, 2021). "Thus, increasing HDAC3 expression may overcome resistance to anti-cancer drugs, including BRAF and MEK inhibitors." (PMID 32626712, 2020). "However, factors that regulate HDAC3 in cancer remain largely unclear." (PMID 29555935, 2018). "Therefore, tubulin β3 is a downstream target of HDAC3 that confers resistance to anti-cancer drugs." (PMID 30583572, 2018). "However, how HDAC3 is regulated in cancer remains largely unclear." (PMID 29555935, 2018). "In addition, the promising findings in the pre‐clinical models suggest that HDAC3 inhibition might lead to appropriate cancer trials in the future." (PMID 29523594, 2018).
cancer (continued). "Thus, HDAC3 can be considered as a target for the development of anti-cancer therapeutics." (PMID 30583572, 2018). "Elucidating the connections between DBC1, HDAC3 and Rev-erbs may have implications for the pathogenesis and treatment of metabolic diseases like obesity, diabetes, liver steatosis, metabolic syndrome and cancer." (PMID 23841676, 2013). "For instance, HDAC3 can protect proteins like POC5 (POC5 centriolar protein), which supports cancer cell proliferation, from degradation." (PMID 40006729, 2025). "One of the earliest HDAC inhibitors approved for cancer treatment is vorinostat (SAHA), which targets multiple HDAC isoforms, including HDAC3." (PMID 40006729, 2025). "Zinc‐dependent HDACs can be subdivided into four classes (class I–IV) based on sequence similarity to yeast deacetylases, among which class I HDACs (HDAC1, HDAC2, HDAC3, and HDAC8) are well studied and proved to be closely related to the development of cancer." (PMID 41267925, 2025). "Among them, St.38 exhibited strong antiproliferative activity across multiple cancer cell lines and potently inhibited CDK9, HDAC1, and HDAC3." (PMID 41440016, 2025). "Consequently, the combination of HDAC3 inhibitors (HDAC3i) and tumor immunotherapy is regarded as a promising new treatment strategy with significant clinical applications and research potential, offering new opportunities to improve the overall prognosis of cancer patients." (PMID 40006729, 2025). "Thus, targeting HDAC3 to impair the ability of FP-RMS cells to activate HR pathway after DNA damage could represents a critical strategy to elicit the radiotherapeutic vulnerability in this cancer type." (PMID 39107280, 2024). "Moreover, HDAC3 depletion also counteracts the IR-dependent induction of ERKs and JNKs phosphorylation/activation status, both known to collaborate in sustaining cancer survival, stem-like population and radioresistance of several cancer types, including in RMS." (PMID 39107280, 2024). "As we found that the expression of HDAC3 was markedly increased in TIP60-knockdown cells, we investigated the expression pattern of HDAC3 in various cancers." (PMID 38805168, 2024). "The expression of HDAC3 was upregulated in various cancers, including COAD, READ, BRCA, and UCEC, while the expression of TIP60 was downregulated in these cancers, suggesting the possibility of a transcriptional repressor role of TIP60 in HDAC3." (PMID 38805168, 2024). "The inhibitory activity of the series 92a–d towards HDAC1, HDAC3, and HDAC6 isoforms and cancer cell proliferation were evaluated." (PMID 38202821, 2024). "The ability of compounds 76a–o to inhibit recombinant human HDAC1, HDAC3, and HDAC6 isoforms and ‘in vitro’ activity against cancer cell lines RMPI 8226 and HCT 116 was tested." (PMID 38202821, 2024). "HDAC3 expression also influenced cancer stemness in PDAC, supporting the opinion that HDAC3 contributes to drug resistance." (PMID 37743465, 2023). "The results showed that HDAC3 silencing reduced the phosphorylation of CDK1 Y15 and STAT3 Y705 followed by reduction of CD44 and Sox2, which resulted in the impairment of cancer cell stemness." (PMID 37743465, 2023). "Honokiol-induced ER stress–activated calpain activity targeted HDAC3 and blocked Tyr298 phosphorylation, subsequently blocked cooperating with EMT transcription factors and cancer progression." (PMID 34973135, 2023). "Histone deacetylase 3 (HDAC3) is a member of histone deacetylase family and exerts a crucial role in the occurrence and development of malignant tumors, particularly in proliferation, apoptosis, angiogenesis, metastasis, and anti-tumor drug resistance." (PMID 37415101, 2023). "Therefore, the lack of Foxa1/2 caused by HDAC3 ablation might have released cancer promoting effect of oestrogen." (PMID 37752418, 2023). "HDAC3 promotes histone H4K16ac, which acts on PI3K and enhances the interaction between LC3 and ATG4 to trigger autophagy that affects cancer cell proliferation." (PMID 37143582, 2023).